CD200 (CD200 molecule)
Diseases named in the same sentence as CD200 in open-access papers (continued):
Sharing a sentence is not in itself a finding about the gene and the disease.
cancer (108 papers, 2010 to 2026). A tumor composed of atypical neoplastic, often pleomorphic cells that invade other tissues. "All tumors showed high expression of these proteins, but multivariable analysis revealed two key factors independently associated with a higher risk of cancer relapse: low CD200 expression and patient immunosuppression." (PMID 40075669, 2025). "While CD200 is traditionally associated with immunosuppression and poor clinical outcomes, recent studies have revealed its diverse effects on different cancer types, stages, and microenvironments." (PMID 38137547, 2023). "CD200 expression has been implicated in cancer progression, particularly through the induction of epithelial-to-mesenchymal transition (EMT)." (PMID 38137547, 2023). "Our results thus uncover a paradigm for CD200 as a potentially novel and targetable NK cell–specific immune checkpoint, which is responsible for NK cell–associated poor outcomes in many cancers." (PMID 36074574, 2022). "The membrane glycoprotein CD200 was originally identified as an immune tolerance-signaling molecule that mainly regulates myeloid lineages and was eventually associated with cancer progression." (PMID 31627350, 2019). "We showed that CD200 exclusively induced EMT, invasion, metastasis, and cancer stemness, which was in agreement with the association of CD200 with cancer stemness and the eventual development of in vivo resistance to chemoradiation." (PMID 31627350, 2019). "Previous studies have suggested that CD200 overexpression is associated with cancer stem cells and resistance to chemoradiation using HNSCC cell lines." (PMID 31627350, 2019). "Many authors reported an association between CD200 and stem cell properties in solid tumors, suggesting that cancer stem cells use CD200 system to prevent the attack of the immune system." (PMID 26338961, 2015). "Overexpression of CD200 has been associated with differential outcomes across cancer types." (PMID 38619621, 2024). "CD200 is upregulated in various cancer types and associated with immunosuppression." (PMID 38137547, 2023). "This cleaved CD200 cytoplasmic domain can subsequently bind β-catenin and translocate into the nucleus where it directly enhances the expression of transcription factors known to be associated with cell proliferation and cancer progression." (PMID 38137547, 2023). "CD200 is also a cancer-associated marker, thus, CD200-negative sorting may also limit the risk of tumorigenesis." (PMID 30410112, 2018). "Moreover, further characterization of CD200 positive BMMSCs in future is critical because CD200 has also been linked to cancer stem cells and tumors." (PMID 22363701, 2012). "Using the deconvolved TCGA-BRCA dataset, we found that patients with high CD200 levels in cancer cells also showed high levels of CD200R1 in NK cells, CD14+ myeloid cells, and Treg, consistent with our observations in mouse models." (PMID 40568095, 2025). "CD200 can also be present on various cell types, including myeloid, lymphoid, epithelial, and cancer cells, as well as on the specific FRC subsets TRCs and FDCs." (PMID 41211809, 2025). "In cancer cells, the expression of four SRGs (PI3, AUP1, CD200 and GNAS) is closely associated with epigenetic regulation and epithelial-mesenchymal signaling." (PMID 40534859, 2025). "CD200 has been recently proposed as a potential new actionable CSC marker in various types of cancer." (PMID 41233805, 2025). "We next generated a dormancy gene signature from our findings that included the expression levels of SLURP1, INFGR2, KLF4, and CD200 in cancer cells along with CD200R1 in NK cells and tested for links to immunotherapy responses." (PMID 40568095, 2025). "Further studies and the application of immune-modulating strategies will be needed to fully develop CD200 as an outstanding therapeutic target in cancer therapy." (PMID 39795972, 2024). "Malignant tissues significantly expressed more CD200 overall than the cancer-adjacent and normal pancreatic tissues." (PMID 38619621, 2024).
cancer (continued). "High CD200 expression has been found to be expressed on several types of cancer, including several hematological neoplasms, malignant melanoma and neuroendocrine tumors." (PMID 38455039, 2024). "CD200 protein acts as an inhibitory immune checkpoint molecule generating an immunosuppressive response in the microenvironment of several cancers including MM." (PMID 38455039, 2024). "It is studies such as these that have fostered exploration of the manipulation of the CD200:CD200R interaction as an adjunctive checkpoint therapy in clinical cancer." (PMID 38540350, 2024). "This interaction provides a potential anti-CD200 therapy or other immune checkpoints in developing immunotherapy against cancer." (PMID 39795972, 2024). "The comparative studies on CD200 expression patterns in cancers are quite unique and deserve mechanistic attention." (PMID 39795972, 2024). "This involves long-term clinical studies that track changes in CD200 expression throughout cancer treatment into remission." (PMID 39795972, 2024). "CD200 can be found on cancer cells like sarcomas, melanoma, and especially in brain tumours, whereas CD200R was detected on MDSCs, Ma, and DCs, and rarely on T cells." (PMID 38892453, 2024). "Among them, the high expression of CD200 is related to the immune escape and poor prognosis of malignant tumors, and the regulatory role of CD44 in cancer stem cells of HNSCC patients has been clarified in recent researches." (PMID 38347320, 2024). "We previously reported CD200 is expressed in the pancreatic TME, and in this report, we are the first to show that CD200 is overexpressed on stromal, immune, and epithelial cells compared to cancer-adjacent tissues and normal tissues." (PMID 38619621, 2024). "Here, we review recent advances and future trends in CD200-targeted therapies for cancer treatments." (PMID 39795972, 2024). "Similar to other immune checkpoint molecules, CD200 plays an important regulatory role in control of autoimmune diseases, infection, allergy, transplantation and cancer." (PMID 38455039, 2024). "An interesting complexity to the CD200:CD200R story comes from recent findings that human carcinoma tissues express not only the full-length CD200 but also a truncated form, CD200tr, previously reported in other models as a likely antagonist to CD200." (PMID 38540350, 2024). "The ongoing exploration of CD200’s roles and therapeutic implications offers hope for improved cancer treatments and underscores the complexity of immune regulation in the fight against cancer." (PMID 38137547, 2023). "Aside from direct CD200/CD200R blockade using monoclonal antibodies, CD200/CD200R signaling has also been investigated in combination with other cancer therapies." (PMID 38137547, 2023). "Drawing from the multiple scientific studies on cancer immunotherapy, we narrowed our focus to CD24 and CD200 as immune checkpoint molecules that are overexpressed in cancer cells." (PMID 37894750, 2023). "First, relative to normal tissue, there is a paucity of information regarding CD200 expression regulation in human cancers." (PMID 36738455, 2023). "In human cancers, deeper knowledge gaps exist in our understanding of the regulation of CD200 expression." (PMID 36738455, 2023). "The CD200–CD200R pathway has gained considerable attention as a crucial target for cancer immunotherapy, primarily because the interaction between CD200 and CD200R assists cancer immune evasion by suppressing immune activity against cancer." (PMID 37894750, 2023). "Further studies showed that a subpopulation of CD200+ CAFs exhibited increased gefitinib sensitivity due to an enhanced pro-apoptotic effect of gefitinib on cancer cells and that downregulation of CD200 expression deprived CAFs of their sensitizing ability." (PMID 37143134, 2023). "Other cancer studies demonstrate the additional ability of the CD200/CD200R pathway to promote the apoptosis of NK cells." (PMID 36756156, 2023).
cancer (continued). "In this review, we summarized and discussed the latest advancements and insights into CD24 and CD200 as emergent immune checkpoint moieties, further delving into their therapeutic potentials for cancer treatment." (PMID 37894750, 2023). "Highly expressed CD200 plays pro-tumorigenic roles in various malignant tumors, including hematopoietic and solid cancers." (PMID 37894750, 2023). "Clinical trials: Further clinical trials are needed to evaluate the safety and efficacy of CD200/CD200R blockade in various cancer types." (PMID 38137547, 2023). "Regardless, modulating the CD200/CD200R axis has garnered clinical interest as a potential immunotherapeutic strategy for cancer therapy, as demonstrated by early-phase clinical trials." (PMID 38137547, 2023). "We now discuss these studies and the proposed anti-tumorigenic mechanisms of CD200 in facilitating cancer growth and metastasis." (PMID 38137547, 2023). "Personalized medicine: Integrating CD200-related information into precision medicine approaches can aid in tailoring treatment plans for individual cancer patients, optimizing therapeutic responses and minimizing adverse effects." (PMID 38137547, 2023). "Numerous research groups have extensively investigated the effects of CD200 on cancer development and aggressiveness in various types of solid cancers." (PMID 37894750, 2023). "More specifically regarding NK cells, evidence from some cancer studies strongly suggests that CD200 activity directly suppresses the cytotoxic mechanisms of NK cells and their ability to produce interferon-gamma (IFN-γ)." (PMID 36756156, 2023). "Hopefully, the finding of regional MEP markers such as CD200 will lead to more insight into their function in tissue homeostasis and cancer." (PMID 35273332, 2022). "Our findings from analysis of the PRECOG and iPRECOG databases has found that cancer patient adverse outcomes related to CD200 expression levels are directly tied to NK cell activation." (PMID 36074574, 2022). "Although CD200 expression in BCC is limited to a small cancer stem cell population, we observed higher levels by both qPCR and Western blotting." (PMID 36074574, 2022). "Up-regulation of CD200 in blood vascular endothelial cells has previously been reported in inflammation and cancer studies, which is crucial to the suppression of CD200R-expressing myeloid cells." (PMID 34199492, 2021). "We then determined the exact pathway which controls the cancer stem cell–specific immune checkpoints CD200 and CD276." (PMID 33932112, 2021). "Our study showed a strong association of CD200 and CD276 expression with cancer stem cells, which implies unique immune features of cancer stem cells and increases the possibility of utilizing immunotherapy to eliminate them." (PMID 33932112, 2021). "Therapeutic strategies involving antibodies against immune inhibitory receptors like PD1, CTLA4, CD200 have been found very beneficial in preventing the progression of specific cancers through augmentation of T cell-mediated immunity." (PMID 35116028, 2021). "Taken together, these data have relevant implications for the immunotherapy of cancer patients with anti-CD200." (PMID 33324560, 2020). "The most recent in vitro studies suggest that blocking this CD200:CD200R1 interaction enhances Th1 responses and that is how the CD200-expressing cancer cells survive immune therapy or a natural immune response." (PMID 30800162, 2019). "As β-catenin is a key regulator of the mesenchymal transition in cancer, we investigated the relationship between CD200 and β-catenin and the resulting changes in EMT and invasiveness." (PMID 31627350, 2019). "So the question has arisen, given this role as a prognostic factor in human blood malignancies, as how CD200 is involved in cancer." (PMID 30800162, 2019). "For example, CD200- and CD200-associated eRNA (CD200e, ENSR00000156542) are positively correlated in 12 cancer types, and Hi-C data supports the interactions in all 20 tissues." (PMID 31594934, 2019).
cancer (continued). "As CD200 overexpression increases resistance to chemoradiotherapy and leads to the acquisition of cancer stem cell-like features, sphere formation and SOX2 expression, which are associated with stem cell pluripotency in HNSCC, were evaluated." (PMID 31627350, 2019). "Taking these results into account, we conclude that CD200 expressed by CAF608 cells is the functional molecule responsible for augmenting the sensitivity of cancer cells to gefitinib." (PMID 28429795, 2017). "We consider CD200-mediated CAF-cancer cell crosstalk to be a promising candidate for the development of novel treatment strategies against acquired resistance." (PMID 28429795, 2017). "CD200 is expressed by cancer cells and other cell types like mesenchymal stem cells, thymocytes, activated T cells, B cells and dendritic cells." (PMID 26243145, 2015). "The data presented here are significant and are a part of a more comprehensive study to further understand the effects of CD200 in cancer, specifically how CD200 expands a MDSC population." (PMID 25598973, 2014). "Similar to CD47, CD200 is overexpressed in many cancers as a mechanism to avoid immunosurveillance detection by CD200R-containing leukocytes." (PMID 25705515, 2014). "It is generally considered that expression of CD200 on cancer cells has a protumor effect based on the following evidence." (PMID 22319630, 2012). "Indeed, the dual role of CD200/CD200R signaling complicates both its pathophysiological significance in cancers and therapeutic targeting." (PMID 40075669, 2025). "Expression of the immunosuppressive type 1 transmembrane glycoprotein, CD200, also known as OX-2 membrane glycoprotein, has been described in various types of cancer stem cells, including BCC, in which expression is restricted to a small population of cancer stem cells." (PMID 41303751, 2025). "Consequently, CD200/CD200R1 blockade has recently been considered a potential target in some forms of cancer." (PMID 40904466, 2025). "HPX is known to modulate the immune system, and this receptor interacts with a cell surface and highly glycosylated protein, CD200, to reduce myeloid activity in inflammation and may block cancer cell activities." (PMID 41384245, 2025). "Anti-CD200 treatments can be useful in cancers where high levels of CD200 are observed." (PMID 39795972, 2024). "Moreover, RBMX was significantly positively associated with CD200, CD276, and butyrophilin like 2 (BTNL2) expression in most types of cancer." (PMID 38214653, 2024). "On the other hand, CD200 was reported to trigger the induction of the immune tolerance, which could be hijacked, in immunotherapy, to attack cancer cells." (PMID 39795972, 2024). "While the blockade of CD200 can enhance the immune responses against tumors, it might also promote inflammation and may, therefore, boost the growth of inflammation-driven cancers." (PMID 39795972, 2024). "This suggests that CD200 expression in these cancers may contribute to treatment resistance and disease aggressiveness." (PMID 38927907, 2024). "Consequently, one of the promising ways of combating CD200-expressing cancers is through targeting CD200/CD200R interactions." (PMID 39795972, 2024). "However, as a regulator of myeloid cell activity, CD200 expression in PDAC CAFs limits the response of cancer cells to PD-1 immune checkpoint inhibitors by enhancing myeloid-derived suppressor cell activity." (PMID 37143134, 2023). "Additionally, it is worthwhile investigating the efficacy of CD200-targeted immunotherapy in conjunction with other forms of immunotherapy and cancer treatments." (PMID 36756156, 2023). "Moreover, CD200 has been investigated as a prognostic factor because of its notably increased expression in various cancers, including hematopoietic and solid malignancies." (PMID 37894750, 2023). "Moreover, the researchers investigated CD200 expression on MDSCs in both cancer patients and healthy patients." (PMID 36756156, 2023).
cancer (continued). "Moreover, CD200/CD200R expression has been linked to epithelial-to-mesenchymal transition and distant metastasis, further illustrating its role in cancer progression." (PMID 38137547, 2023). "More specifically, blocking the CD200/CD200R pathway may result in hyperactive inflammation that could exacerbate the symptoms of cancer patients receiving immunotherapy." (PMID 36756156, 2023). "In the present review, we summarize the recent progress and understanding of CD24 and CD200 as emerging immune checkpoint signals in cancer as well as their interaction with their cognate receptors, sialic acid-binding immunoglobulin (Ig)-like lectin 10 (Siglec-10) and CD200 receptor (CD200R)." (PMID 37894750, 2023). "The findings from both the CLL and GBM studies suggest that a soluble form of CD200 may further enhance immunosuppression and the development of select cancers." (PMID 36756156, 2023). "Inhibiting immunosuppressive factor CD200 may suppress cancer stem cells and evade the immune system by inhibiting tolerogenic response." (PMID 37752544, 2023). "Further, there are several lines of evidence suggesting that the immunosuppressive capacity of CD200 may also stimulate cancer growth by decreasing the immune response against cancer cells." (PMID 35326506, 2022). "Next, we wondered whether a subpopulation of cancer cell stems have the dual capabilities of resistance to the innate and adaptive immune system through synchronous expression of CD200 and CD276." (PMID 33932112, 2021). "CD200 is a type 1 cell membrane glycoprotein (GP) of the immunoglobulin supergene family that is expressed by many cell types (e.g., B cells, a subset of T cells, endothelial cells, cancer cells)." (PMID 35186014, 2021). "CD200 is a type-1 cell membrane glycoprotein of the immunoglobulin supergene family, present on both cells with myeloid/lymphoid origin as well as on epithelial cells and many cancer cells." (PMID 33562512, 2021). "MIR100HG was significantly correlated with the expression of CD200, CD274 and CD276 in pan‐cancers and was significantly associated with the abundance of central memory CD8 T cells, effector memory CD4 T cells and effector memory CD8 T cells in pan‐cancers." (PMID 33797188, 2021). "In previous studies, CD200 was reported to take part in several cancers." (PMID 32856848, 2020). "Taken together, CD200 exclusively modulates EMT in malignant tumors such as HNSCC." (PMID 31627350, 2019). "It was proposed that treatment with blocking anti-CD200 antibodies might be beneficial for patients with CD200-expressing cancers." (PMID 30653571, 2019). "Further studies are needed to determine whether the function of CD200 observed in HNSCC is applicable to various carcinomas." (PMID 31627350, 2019). "As CD200 maximizes the effect of gefitinib, it could reduce the number of drug-tolerant cancer persister cells." (PMID 28429795, 2017). "This suggests that CD200 exerts by interacting with a yet unknown receptor of cancer cells, whose activation triggers a pro-apoptotic signal cascade only upon EGFR-TKI treatment, through a pathway distinct from PI3K-Akt and/or ERK signaling." (PMID 28429795, 2017). "Therapeutic CD200 mAb are being evaluated for cancers where blocking the inhibitory signal may enhance the homeostatic mechanisms and give increased phagocytosis of the cancer or enhance immune responses against the cancer." (PMID 23691022, 2013). "Expression of CD200 has been found in multiple types of cancer." (PMID 22319630, 2012). "CD44/CD24, CD29, CD133, CD200 are the cancer stem cell marker for breast cancer." (PMID 22082307, 2011). "CD133, CD200 are the cancer stem cell marker for brain cancer." (PMID 22082307, 2011). "Moreover, we observed individual cancer cells within capillary-like CD200+ lymphatics, suggesting that cancer cells may disseminate through these lymphatics for systemic spread." (PMID 41249124, 2025).